ZNF684 (zinc finger protein 684)
Description:
May be involved in transcriptional regulation.
Synonyms: MGC27466
Tractability: PROTAC: ubiquitination databases record sites on it.
Gene: Protein-coding gene on chromosome 1 (40,531,573 to 40,548,168, forward strand). Ensembl gene ENSG00000117010.
Subcellular location: Nucleus
Subcellular location (Human Protein Atlas): Cytosol; Nucleoplasm
Pathways (Reactome):
Gene expression (Transcription): Generic Transcription Pathway
Gene Ontology:
Molecular function: sequence-specific double-stranded DNA binding; DNA-binding transcription factor activity, RNA polymerase II-specific; RNA polymerase II transcription regulatory region sequence-specific DNA binding
Biological process: regulation of transcription by RNA polymerase II; regulation of DNA-templated transcription
Cellular component: nucleus
Genetic constraint (gnomAD): Loss-of-function variants: 10 observed, 11.18 expected, observed/expected ratio (o/e) 0.89, 90% interval 0.55 to 1.51. The synonymous counts are far from expectation, so gnomAD's model fits this gene poorly and the ratio says little. Missense variants: 384 observed, 468.8 expected, observed/expected ratio (o/e) 0.82, 90% interval 0.75 to 0.89. Synonymous variants: 118 observed, 160.61 expected, observed/expected ratio (o/e) 0.73, 90% interval 0.63 to 0.86.
Homologues: Orthologues: chimpanzee ZNF684 (97% identical), macaque ZNF684 (94% identical), dog ZNF684 (85% identical), pig ZNF684 (85% identical), Drosophila melanogaster CG3281 (31% identical), Drosophila melanogaster CG2712 (27% identical), Drosophila melanogaster Phs (21% identical). Paralogues in human: ZNF582 (47% identical), ZNF25 (47% identical), ZNF805 (45% identical), ZNF248 (44% identical), ZNF264 (44% identical), ZNF599 (44% identical), ZNF614 (44% identical), ZFP90 (43% identical), ZFP37 (42% identical), ZNF19 (42% identical), ZNF619 (42% identical), ZNF674 (42% identical), and 50 more.
Diseases named in the same sentence as ZNF684 in open-access papers:
ZNF684 is named in the same sentence as 1 disease in open-access papers, as found by Europe PMC text mining. Sharing a sentence is not in itself a finding about the gene and the disease. The quoted sentences say what the papers report.
depression (1 paper, 2022). "SPACOX identified multiple candidate loci for overall MD status, depression and SUD, such as rs139813674 (P value = 8.39 × 10–9, ZNF684) for overall MD status, rs7231178 (DCC, P value = 2.11 × 10–9) for depression, and rs10228494 (FOXP2, P value = 6.58 × 10–10) for SUD." (PMID 35017462, 2022).